WBP2 (WW domain binding protein 2)
Diseases named in the same sentence as WBP2 in open-access papers (continued):
Sharing a sentence is not in itself a finding about the gene and the disease.
osteosarcoma (1 paper, 2023). A usually aggressive malignant bone-forming mesenchymal neoplasm, predominantly affecting adolescents and young adults. "Even the role of WBP2 in osteosarcoma remains clarified; the downregulation of WBP2 by val-miR218 might contribute to its inhibitory effect in osteosarcoma." (PMID 39698025, 2023).
polycystic kidney disease (1 paper, 2021). A usually autosomal dominant and less frequently autosomal recessive genetic disorder characterized by the presence of numerous cysts in the kidneys leading to end-stage renal failure. "It is noted that YAP/TAZ knockout embryos suffer from premature death or polycystic kidney disease, while WBP2 knockout mice are reported to be viable with defects in hearing and other behaviours related to nervous system, metabolism and epidermal cell regeneration." (PMID 34831354, 2021).
cancer (16 papers, 2015 to 2026). A tumor composed of atypical neoplastic, often pleomorphic cells that invade other tissues. "High expression of WBP2 is involved in the Wnt/β-catenin pathway and linked to cell proliferation and invasion in cancer tissues." (PMID 38239300, 2024). "The WW-domain binding protein 2 (WBP2) is an emerging oncoprotein that has been implicated in several cancers, especially in the breast." (PMID 34831354, 2021). "Having shown that ENO1 and Homer3 mediated cancer cell growth and metastasis induced by WBP2 overexpression, we explored the underlying mechanism of WBP2 acting as a key regulator of tumor development." (PMID 29497031, 2018). "Furthermore, the GEPIA online correlation database (gepia.cancer-pku.cn) revealed a positive association between WBP2 and YAP target genes, including CTGF, CYR61, and AREG." (PMID 33837178, 2021). "Does WBP2 associate with these scaffold proteins to inhibit Hippo signalling in cancers?" (PMID 34831354, 2021). "This study reported a novel role of WBP2 in cancer metabolism and energetics that contributes new insights into the molecular etiology of cancer." (PMID 41744824, 2026). "COX-2, WBP2, IFITM3, and SFRP4 are associated with cell proliferation and inflammation in a variety of cancers." (PMID 38239300, 2024). "In this study, we tapped into the potential of integrated proteogenomic analysis to delineate the sophisticated signaling network modulated by cancer oncogene, particularly WBP2, in TCGA BRCA." (PMID 34197030, 2022). "Spearman correlation analysis confirmed that WBP2 copy number is positively but only moderately correlated with WBP2 mRNA z‐scores across the samples in TCGA Pan‐cancer Atlas." (PMID 34197030, 2022). "Given the intricate link between WBP2 and Hippo signalling, targeting WBP2 can be used in combination with currently clinically available drug to minimise drug resistance and induce the Hippo pathway to curb cancer progression." (PMID 34831354, 2021). "This highlights the immense potential of WBP2 to drive oncogenic processes in even more cancer types than what has been suggested in the current literature." (PMID 34831354, 2021). "It will be interesting to explore how the interplay between WBP2 and the Hippo pathway mediates miRNA biogenesis in cancers." (PMID 34831354, 2021). "A staggering number of studies have substantiated the transcriptional co-activator role of WBP2 in a myriad of cancers." (PMID 34831354, 2021). "Concurrently, in vitro and in vivo studies demonstrated that WBP2 was a promoter of cancer proliferation, migration and invasion." (PMID 34831354, 2021). "Accordingly, an evaluation of WBP2 at its protein level is likely to be more clinically relevant than assessing its mRNA level for cancer therapeutics." (PMID 34831354, 2021). "The intricate loop between WBP2 and the Hippo pathway can be potentially exploited for tailored therapeutic strategies in WBP2-driven cancers." (PMID 34831354, 2021). "Ultimately, the intricate loop involving WBP2 and the Hippo pathway provides multiple feedback mechanisms to boost the WBP2 level and inhibit Hippo signalling, resulting in a culminative equilibrium shift toward WBP2-driven cancer signalling." (PMID 34831354, 2021). "In this section, we review the structure and function of WBP2, with a focus on its pro-tumorigenic roles in human cancers." (PMID 34831354, 2021). "Here, we elaborate on the modes of action of WBP2 in regulating the Hippo signalling pathway in cancers." (PMID 34831354, 2021). "Henceforth, the ability of WBP2 to mediate the activity of multiple TFs means that it has high potential to act as a therapeutic target in cancers with dysregulated TF activity." (PMID 34831354, 2021). "In summary, an elucidation of the key mechanisms orchestrating WBP2 expression in cancer has enabled us to design therapeutic strategies against WBP2 at transcriptional, post-transcriptional or post-translational levels." (PMID 34831354, 2021).
cancer (continued). "Further delineation of WBP2 and its implications in LATS1/2 kinase activity will provide more insights into the development of anti-WBP2 therapeutics for Hippo-dysregulated cancers." (PMID 34831354, 2021). "Given WBP2’s multimodal actions, we envisage that even more mechanistic actions of WBP2 will be revealed in a wider range of cancer types." (PMID 34831354, 2021). "In summary, repression of Hippo signalling through MST1/2 is likely to augment WBP2 expression, generating a positive feedback loop to further suppress Hippo signalling and drive cancer progression." (PMID 34831354, 2021). "Here, we summarise the biological mechanisms of WBP2/Hippo reciprocal regulation and propose therapeutic strategies to overcome Hippo defects in cancers through targeting WBP2." (PMID 34831354, 2021). "The ability of WBP2 in activating a myriad of oncogenic pathways indicates that WBP2 is a putative novel biomarker and drug target for WBP2+ cancer." (PMID 32393834, 2020). "To gain better insights into the molecular etiology of cancer, we review the molecular mechanisms by which WBP2 exerts its oncogenic function." (PMID 32393834, 2020). "Interesting, the other three cancers (breast, ovarian, and prostate) with high WBP2 protein level are hormonally regulated." (PMID 32393834, 2020). "Other cancer types that showed upregulation of WBP2 gene expression in the TCGA database include kidney renal papillary cell carcinoma, kidney renal clear cell carcinoma, and thyroid carcinoma." (PMID 32393834, 2020). "This review focuses on the more recent advances in the oncogenic function and regulation of WBP2 oncoprotein, as well as its potential utilities in cancer detection, therapy, and precision medicine." (PMID 32393834, 2020). "The robust oncogenic effect of WBP2 as a result of its transcription coactivator role suggests that WBP2 has a wider role in other oncogenic signaling cascades, human cancer types and diseases." (PMID 32393834, 2020). "To date, an EVH1-containing protein Homer3 has been shown to interact with WBP2, which drives the PI3K pathway-mediated oncogenic properties of WBP2 in cancer." (PMID 32393834, 2020). "WBP2 expression was profoundly increased when normal mammary epithelial and cancer cell lines were subjected to ITCH knockdown or treatment with proteasomal inhibitors." (PMID 32393834, 2020). "Moving forward into the next decade, we expect to see WBP2 playing a wider role in human cancers and diseases, signal transduction pathways, and precision medicine." (PMID 32393834, 2020). "Understanding how the pleiotropic WBP2 oncogene is regulated has a significant impact on the management of cancer." (PMID 32393834, 2020). "Taken together, WBP2 exerts its oncogenic function by activating a variety of signaling pathways, driving tumorigenesis and cancer progression/migration in a wide range of human cancers." (PMID 32393834, 2020). "Another avenue is to activate ITCH E3 ubiquitin ligase that should lead to downregulation of WBP2 expression and cancer growth." (PMID 32393834, 2020). "Taken together with the previous findings that WBP2 positively regulates PI3K/Akt pathway, the presence of a positive feedback loop between PI3K/Akt and WBP2 is envisaged to drive cancer processes." (PMID 32393834, 2020). "Over the past decade, WBP2 surfaced as a key node connecting key signaling pathways associated with ER/PR, EGFR, PI3K, Hippo, and Wnt in cancer." (PMID 32393834, 2020). "Previous study has indicated that E3 ligase ITCH can bind and target WBP2 for ubiquitin-dependent proteasomal degradation resulting in the downregulation of WBP2 level and dysfunction in cancer." (PMID 29937544, 2018). "Other known Hpo-independent regulators of Yki include the phosphatase PTPN14 and the WW domain binding protein WBP2, which were identified in mammalian cancer cell lines." (PMID 25643260, 2015).
cancer (continued). "Therefore, WBP2 protein expression is likely to a better reference than gene expression or copy number to evaluate the effects of WBP2 in cancer progression." (PMID 34197030, 2022). "This brings about the possibility that in cancer types with lower WBP2 amplification frequencies, transcriptional or posttranscriptional control of WBP2 may be the main factor regulating WBP2 mRNA abundance." (PMID 34197030, 2022). "It is conceivable that WBP2 could be involved in the control of mRNA stability of oncogenes other than BTRC to drive cancer biology." (PMID 34197030, 2022). "In fact, the involvement of WBP2 in MPC assembly may provide mechanistic clues to explain the global suppression of miRNAs often observed in cancer patients." (PMID 34831354, 2021). "Our finding that WBP2 is regulated by miRNA is supported by the fact that a few miRNAs have been reported to negatively regulate WBP2 and mRNA levels in various cancer models, and these comprise of miR-613, miR-19a, miR-19b, miR-23a, miR-27a, miR-206, miR-485 and miR-613." (PMID 34831354, 2021). "This wide array of drugs constitutes an arsenal of Hippo targeting agents that could be used together with WBP2-targeting agents to achieve a combinatorial effect for cancer therapy." (PMID 34831354, 2021). "We envision that WBP2 may act as a neoteric mechanotransduction modulator to regulate the Hippo signalling pathway in cancers." (PMID 34831354, 2021). "Understanding the modes of action of WBP2 and its interaction with E3 ligases may provide novel avenues for cancer therapeutic strategies." (PMID 34831354, 2021). "Further characterisation of the phenotypical and mechanistic roles of WBP2 in more cancer types may expand the scope for effective WBP2 therapeutic targeting." (PMID 34831354, 2021). "Consequently, targeting WBP2 at its PY motif is a plausible therapeutic strategy to limit WBP2-driven cancer progression." (PMID 34831354, 2021). "Given the dysregulation of Hippo and WBP2 signalling in cancers, targeting WBP2 may be a viable option to curb Hippo-suppressed and WBP2-driven cancer initiation and progression." (PMID 34831354, 2021). "Moreover, WBP2 amplification was found in several other cancers, such as ovarian, cervical and pancreatic cancers." (PMID 34831354, 2021). "WBP2’s role in other human cancer types has also been reported." (PMID 32393834, 2020). "Understanding how WBP2 is regulated has important implications for cancer therapy." (PMID 32820148, 2020). "Finally, we envision new trends in WBP2 research in the space of molecular etiology of cancer, targeted therapeutics, and precision medicine." (PMID 32393834, 2020). "Possibly, both ablation of WBP2 in drug-resistant cancer cells and combination of ER inhibitor and chemotherapy facilitated the absorption of chemotherapy drugs and sensitised ERα-positive drug-resistant cancer cells to chemotherapeutics." (PMID 29937544, 2018). "Since WBP2 has been shown to play oncogenic roles in multiple cancers in the brain, liver, and gastric, we wanted to gain a more comprehensive insight into the dysregulation of WBP2 using TCGA Pan‐cancer Atlas, an cancer databases comprising 11 000 samples across multiple tumor types." (PMID 34197030, 2022). "WW domain-binding protein 2 (WBP2) is an emerging oncoprotein profoundly implicated in a variety of transduction systems, such as Wnt, Hippo, epidermal growth factor receptor (EGFR) and steroid signaling pathways, and human cancers including breast malignancies." (PMID 34117091, 2021). "While direct studies on WBP1 in cancer are limited, other WW domain-binding proteins, such as WWP1 and WBP2, have been demonstrated to play crucial roles in cancer metabolism." (PMID 40075333, 2025). "On the other hand, WBP2 mRNA expression seems to be controlled by WBP2 copy number to a greater extent in TCGA OV and UCS, as compared to the other cancer types." (PMID 34197030, 2022).
cancer (continued). "Consistently, current findings on the link between WBP2 and MST/LATS/YAP have clear implications on uncontrolled cell proliferation and cancer aggressiveness." (PMID 34831354, 2021). "It will be intriguing to explore how WBP2 can interfere with the YAP–p73 interplay, and decipher the relevant translational implications in cancers." (PMID 34831354, 2021). "For example, TAZ and Nedd4 WW domains interact with the WBP2 PY2 motif, ITCH WW domains 1 and 3 interact with WBP2 PY2 and PY3 motifs to regulate cancer growth, while WWOX and YAP WW domains interact with PY3." (PMID 32393834, 2020). "Upregulation of WBP2 in MCF7 cells increased the chemoresistance to doxorubicin, while RNAi-mediated knockdown of WBP2 in MCF7/ADR cells sensitised the cancer cells to doxorubicin." (PMID 29937544, 2018). "We evaluated the expression of ENO1 in several cancer cell lines and found that ENO1 and Homer3 were potent partners of WBP2 in U251 cells." (PMID 29497031, 2018). "There is a lack of comprehensive meta‐analysis of WBP2 on a genomic, transcriptional, and protein level in large‐scale cancer databases." (PMID 34197030, 2022). "Taken together, the discovery of the non-transcriptional roles of WBP2 provides new opportunities to target cancers with alterations in non-transcriptional processes." (PMID 34831354, 2021). "Given that both nuclear and cytosolic WBP2 have defined molecular functions in the Hippo pathway, we postulate that directing WBP2 cellular localization is not a tenable anti-cancer avenue to modulate the Hippo pathway." (PMID 34831354, 2021). "We posit that elucidating the structural interactions of WBP2 and YAP/TAZ may serve as a possible therapeutic direction especially in cancers with WBP2 and YAP/TAZ overexpression." (PMID 34831354, 2021). "Follow-up studies revealed that E855K ITCH mutant indeed could not abolish WBP2-mediated cancer growth in vitro and in vivo." (PMID 32393834, 2020).
tumor (13 papers, 2017 to 2024). "The tumour weight loss caused by drug treatment was lower due to WBP2 overexpression, compared to the doxorubicin-treated control mice." (PMID 29937544, 2018). "To sum up, we identified EIF4A3-mediated circPRKCI expression acts as a tumor-promoter in TNBC through regulating WBP2 and PI3K/AKT signaling pathway via serving as miR-545-3p sponge, providing a novel providing a new avenue of therapy for TNBC." (PMID 35236829, 2022). "It is widely accepted that WBP2 is involved in multiple tumor-promoting signaling pathways and plays a dominant role in tumorigenesis." (PMID 35236829, 2022). "Nevertheless, our group has previously reported that WBP2 silencing diminished tumor growth in TNBC xenografts." (PMID 34197030, 2022). "In conclusion, WBP2 interacts with the components of the microprocessor complex, leading to the suppression of microprocessor complex assembly and its putative tumor suppressor function." (PMID 34117091, 2021). "A cell-permeable sequence designed to inhibit the C terminus of WBP2 can be tagged with a therapeutic protein and delivered into the tumour to disrupt the interactions between WBP2 and its binding partners." (PMID 34831354, 2021). "2D and 3D in vitro proliferation assays revealed that WBP2 blocked the tumor-suppressive properties of DGCR8, a key component of the microprocessor complex." (PMID 34117091, 2021). "WBP2 protein blocks the microRNA biogenesis via physical interactions with the microprocessor complex, and reverts the tumor-suppressive role of DGCR8." (PMID 34117091, 2021). "WBP2-overexpressing HeLa tumor xenografts in the MST1-K59R mice group appeared to form larger tumors when compared to the vector control (WBP2 alone) group." (PMID 32820148, 2020). "Most studies of WBP2 have focused on its function as a coactivator of ER, and its role in promoting tumor cell proliferation in ER-positive tissue or cell lines." (PMID 29497031, 2018). "Compared with PBS-treated mice, tumours from both the control group and the WBP2 overexpression group were significantly suppressed after doxorubicin treatment." (PMID 29937544, 2018). "The tumour sizes of WBP2 overexpression group treated with doxorubicin were larger than control group mice." (PMID 29937544, 2018). "Limiting the expression of endogenous WBP2 suppresses, whereas overexpression of WBP2 enhances, the transformation and transcription-promoting ability of TAZ, suggesting WBP2 is a crucial part of TAZ-launched tumor cell metastasis." (PMID 28724435, 2017). "To further verify whether WBP2 exerts similar effects in vivo, we performed subcutaneous tumor transplantation and lung metastasis experiments following tail vein injections in nude mice." (PMID 33837178, 2021). "The in vitro proliferation assays further showed that WBP2 could revert the proposed tumor-suppressive property of DGCR8." (PMID 34117091, 2021). "As the function of WBP2 is intricately linked to YAP and TAZ, we hypothesize that WBP2 is negatively regulated by the Hippo tumor suppressor pathway." (PMID 32820148, 2020). "This raises a testable hypothesis that WBP2 plays a role in the NF-κB and integrin signaling pathways to regulate tumor microenvironment and remodeling of the extracellular matrix to facilitate tumorigenesis, angiogenesis, and metastasis." (PMID 32393834, 2020). "The study offers new insights into the regulation of the WBP2 oncogene by the MST tumor suppressor." (PMID 32820148, 2020). "However, the difference was not statistically significant, indicating that the bulk of the in vitro and in vivo tumor growth from WBP2-WT and MST1-K59R co-expression were contributed by WBP2." (PMID 32820148, 2020). "WBP2 upregulation obviously promoted tumor growth in comparison with the control group." (PMID 29497031, 2018). "We further explored whether mice body weight would affect the tumour size of doxorubicin-treated controls and WBP2 overexpression mice." (PMID 29937544, 2018).